IRF5 (interferon regulatory factor 5)
Diseases named in the same sentence as IRF5 in open-access papers (continued):
Sharing a sentence is not in itself a finding about the gene and the disease.
infection (continued). "This suggests that macrophages can restrict WNV-NY infection through an alternative pathway that is independent of IRF-3, IRF-5, and IRF-7, possibly through IRF-1 and/or other transcription factors." (PMID 23300459, 2013). "Despite the combined absence of IRF-3, IRF-5, and IRF-7, TKO mice still produced type I IFN after WNV infection, albeit at lower levels in the context of markedly enhanced infection." (PMID 23300459, 2013). "As IRF-5 also has been implicated in IFN production and protection in vivo after infection by negative strand RNA viruses (Newcastle Disease virus (NDV) and VSV) and DNA viruses (HSV), we evaluated whether the transcriptional signal after WNV infection of mDC cells was dependent on IRF-5." (PMID 19798431, 2009). "While knockdown of IRF3, IRF5, or IRF7 expression had no impact on the efficiency of infection establishment, we observed significant downregulation in IP-10 expression upon IRF5 or IRF3 knockdown and a trend toward significance upon knockdown of IRF7 expression in HIV-infected MDMs." (PMID 40493408, 2025). "Furthermore, after infection of iPS-DCs with IAV, IRF5 was detected in Kolf2 iPS-DCs and not IRF5−/− iPS-DCs by immunostaining." (PMID 32075938, 2020). "However, we observed stronger Th1 responses in Irf5-/- mice during the first two weeks of infection, suggesting that priming of Th1 cells was more effective in the absence of IRF-5 and that IRF-5 is mainly needed for sustaining Th1 responses." (PMID 26046638, 2015). "In the absence of IRF-5, CD8 T cells enter the cell cycle in greater proportion; however, they fail to accumulate, display reduced survival capacity, and show increased signs of functional exhaustion during the chronic stage of infection, when compared with IRF-5 sufficient cells." (PMID 40494997, 2025).
cancer (55 papers, 2010 to 2026). A tumor composed of atypical neoplastic, often pleomorphic cells that invade other tissues. "Mechanistic studies via overexpression and/or knockdown/knockout of IRF5 in immortalized cancer cell lines reveal functional links between loss of IRF5 and increased cell proliferation, migration, and invasion in vitro, and in vivo." (PMID 38969706, 2024). "To determine if IRF5/IKKβ-encoding NPs can reprogram M2 macrophages into the therapeutically desirable anti-cancer M1 phenotype, we used NanoString gene expression analysis." (PMID 31481662, 2019). "Given that dysregulated IRF5 expression has been implicated in the pathogenesis of numerous diseases, including autoimmune and cancer, results indicate that caution should be used in the evaluation and interpretation of IRF5 expression analysis." (PMID 27481535, 2016). "Similarly, IRF5, implicated in the metabolic response of airway macrophage, hinted at potential functions in cancer, demanding further validation." (PMID 39393173, 2024). "Loss of IRF5 has also been shown to correlate with disease stage and metastasis in cancers and may constitute another mechanism underlying resistance of advanced tumors to IFN-therapies." (PMID 30186768, 2018). "In support of this hypothesis, loss of IRF5 expression has been observed in many cancers including breast, lung, hepatocellular, gastric, colon and hematological malignancies." (PMID 25649192, 2015). "The genes BLK, CDC247, CSK, IRF5, STAT1, STAT4, and TNIP1 are associated with AIDs, and CDC37, DDX6, HSPA6, MAPT, PPIB, STAT1, and STAT4 are associated with cancers." (PMID 40429780, 2025). "A more thorough understanding of the mechanisms by which IRF5 alters EV release from cancer cells and leads to a protective metastatic environment is also warranted." (PMID 38969706, 2024). "The significance of solo-LTR-derived mRNAs has been established in various cancers, such as interferon regulatory factor-5 (IRF5) and anaplastic lymphoma kinase (ALK) isoform ALKATI." (PMID 38606358, 2024). "While IRF5 has distinct cell type-specific roles, its effect on the behavior of various cancers differs, including in some instances, malignancies in which it has been reported as an oncogene." (PMID 38969706, 2024). "In this study, we generated M1‐like macrophage exosomes overexpressing IRF5, referred to as IRF5 M1‐exos, for potential cotherapy in cancer treatment." (PMID 39623605, 2024). "Upon whole-body pre-conditioning with t-dEVs from IRF5-high or -low OS and BC cells, we found increased lung metastatic colonization that replicated findings from orthotopically implanted cancer cells." (PMID 38969706, 2024). "Conversely, re-expression of IRF5 in cancer cells that have otherwise ‘lost’ expression, results in regained cell growth control." (PMID 38969706, 2024). "Collectively, our findings uncover a new role for IRF5 in cancer metastasis through its regulation of t-dEV programming of the PMN." (PMID 38969706, 2024). "Promoter onco-exaptation, as suggested for the variant MIR3 SINE or HERV-L MSTA LTR, has been observed for many cancers, e.g., IRF5 driven by the demethylated LOR1a LTR in HL." (PMID 39770638, 2024). "For example, YTHDF1 expression had a strong association with STAT1 in Th1 cells, STAT6 in Th2 cells, STAT3 in Th17 cells, STAT5B in Treg cells, BCL6 in Tfh cells, and IRF5 in M1 macrophages in most cancer types." (PMID 34026603, 2021). "Knockdown of FBXL8 in BRCA cells resulted in the accumulation of CCND2 and IRF5, concomitant with cancer suppression." (PMID 32784654, 2020). "IRF5 is a transcription factor, purported to be a cancer-suppressor which regulates apoptosis and immune activation." (PMID 32784654, 2020). "Altogether, our computer modeling prediction and retrospective studies highlight the potential role of FBXL8 E3 ligase in specific degradation of CCND2 and IRF5 proteins as cancer progresses." (PMID 32784654, 2020).
cancer (continued). "The master transcription factor IRF5 has been involved in the occurrence and progression of numerous diseases, including cancer." (PMID 31681610, 2019). "Endogenous IRF5 expression was low to undetectable in all three carcinoma cell lines examined, while relatively high levels are expressed in the normal epithelial counterpart." (PMID 25649192, 2015). "This preliminary data suggests that PHY906 works in the context of chemotherapy by enhancing inflammation through IRF-5 while blocking the anti-apoptotic effects likely activated by cancer cells through the suppression of IRF-1 expression." (PMID 21569348, 2011). "Nevertheless, the differential expression of EGFR and VEGFc, in addition to MMP9 and CXCL5, differentially packaging into IRF5-low versus IRF5-high EVs across two cancer types provide insight into the mechanisms by which IRF5 contributes to protection from PMN formation." (PMID 38969706, 2024). "Schematic illustration of IRF5 M1‐exos: (A) shows the schematic presentation showing the preparation process of IRF5 M1‐exos; (B) shows the scheme showing the effects of IRF5 M1‐exos against cancer; and (C) shows the mechanism of anticancer effect of IRF5 M1‐exos." (PMID 39623605, 2024). "Of particular interest, we identified several proteins that were significantly enriched in IRF5-negative EVs that have been associated with more aggressive cancers and poorer prognoses." (PMID 38969706, 2024). "Notably, PTPN1, TRIM46, TRIM17, FCGR1A, IRF5, IRF6, and CAMK2B had a higher frequency of gain mutations in most human cancer types." (PMID 37941546, 2023). "Given the role of IRF5 in pathogenesis, its clinical and prognostic value in cancer, IRF5 may represent a potential therapeutic target for cancer." (PMID 31681610, 2019). "Together, these data suggest that multiple mechanisms may exist that regulate IRF5 expression and function in cancer." (PMID 22053985, 2011). "Furthermore, for many of these TFs, such as TFEC, IRF5, and ERF, we found a significant association between TF expression and cancer prognosis using TCGA data, suggesting that the dysregulation of these TFs can also impact cancer outcomes." (PMID 39013578, 2024). "Additionally, PHY906 enhanced the expression of IRF-5, another potent pro-inflammatory transcription factor associated with immune-mediated, tissue-specific rejection as well as induction of apoptosis of CPT-11 treated cancers." (PMID 21569348, 2011). "In the present study, we found that TNF, IFN, IRF1 and IRF5, IL-6, IL-1β, and CCL3 were upregulated in EBV-positive SCC25 cancer cells compared to EBV-negative SCC25 cancer cells." (PMID 39941858, 2025). "Of significance is that FBXL8 is a specific protein degradation enzyme which selectively targets cancer suppressors like CCND2 and IRF5." (PMID 32784654, 2020). "We showed a novel molecular mechanism underlying the specific interaction of the pro-tumorigenic FBXL8 with two cancer suppressors, CCND2 and IRF5, resulting in their downregulation." (PMID 32784654, 2020). "It has been demonstrated that microRNA-146a can target many genes, such as IRAK1, IRAK2, TRAF6, RIG-I, IRF-5, STAT-1, PTC1, Numb, and WASF2, to play a variety of roles in human diseases, including cancers and inflammatory immune diseases." (PMID 31798643, 2019). "To date, only limited targets including miR-155, IRF5, Blimp1, CCNB1, BCL6, CDK6, Myc, and several others have been identified as IRF4 targets in cancers." (PMID 25207815, 2014).
cancer (continued). "Interestingly, TAMs (CCL2, CD86, and IL10), M1 [INOS(NOS2), IRF5, and COX2(PTGS2)] were significantly correlated with SHC1 expression in the three cancers." (PMID 35601500, 2022). "The model we created and based on the expression of 3 genes, BATF3, IRF5, ZBTB38, could help in the prediction of the reaction and prognosis of cancer patients given platinum-based, especially cisplatin-including chemotherapies." (PMID 35410350, 2022). "Thus, the target proteins of the TRAF2/TRAF3 complex, namely, NF-kappaB-inducing kinase (NIK), c-Rel, and interferon regulatory factor 5 (IRF5), are activated, which upregulates inflammation-related genes and stemness-related genes in cancer cells." (PMID 34454495, 2021). "We next investigated whether anti-cancer CCND2 and IRF5 are binding partners of FBXL8, with a view to providing explanations on how their interactions might impact BRCA progression." (PMID 32784654, 2020). "While FBXL8 promotes cancer growth/metastasis, CCND2 and IRF5 suppress cancer progression." (PMID 32784654, 2020). "Notably, among the predicted list of FBXL8-binding factors, two cancer suppressors, Cyclin D2 (CCND2) and Interferon Regulatory Factor 5 (IRF5), emerged prominently as potential interaction partners of FBXL8." (PMID 32784654, 2020). "Since IRF-5 has been reported to stimulate inflammatory genes, the involvement of IRF5 indicates how FBXL8 might indirectly influence the cytokine profiles, hence promoting a pro-inflammatory cytokine-rich cancer microenvironment, as our results alluded to." (PMID 32784654, 2020). "Conversely, in the case of cancer, IRF5 expression is often found to be downregulated (or absent) in malignant versus non-malignant cells." (PMID 27481535, 2016). "We analyzed cell lines grown from 9 metastases to test the weight of the IRF5 genotype on the intrinsic biology of cancer cells independent of microenvironment influences." (PMID 22909381, 2012). "Similarly, for INMON, FOXO3 and IRF5 were common TFs in healthy and early-stage tissues (e.g., BRCA1-mut); specifically, PRDM4 was the TF in precancer stages (e.g., Goiters and HT) while ATF2 and RUNX1 were enriched in cancers (e.g., ESCC and IDC)." (PMID 38645221, 2024). "Interestingly, among pan-cancer, LGG showed the most significant correlation between GLA with CD86 (P=4.52e-27), CSF1R (P=8.17e-09),CCL2 (P=3.98e-14), CD68 (P=2.37e-34), IL10 (P=3.29e-21), IRF5 (P=8.5e-25), CD163 (P=3.8e-26), VSIG4 (P=9.17e-16) and MS4A4A (P=1.39e-21)." (PMID 37057282, 2023). "To test whether differences between IRF5 genotype bear any effects on the intrinsic biology of cancer cells without the influence of the microenvironment, we cultured the 9 cell lines with or without IFNα and compared transcriptional patterns according to their IRF5 rs10954213 genotype." (PMID 22909381, 2012).
bacterial infection (6 papers, 2012 to 2022). "Altogether, these results indicate that TIRAP can influence IRF5-mediated TLR8 signaling also during bacterial infection, which is especially clear for the induction of IL-12A expression by GBS." (PMID 35884781, 2022). "In accordance with our study, expression of IRF5 in half-smooth tongue sole was significantly increased post bacterial infection in vivo." (PMID 27350041, 2016). "Silencing of Irf5 has not previously been tested as a means to slow or eliminate bacterial infections." (PMID 29773788, 2018).
inflammation (4 papers, 2021 to 2025). Aberrant reaction of the microcirculation characterized by movement of fluid and leukocytes from the blood into extravascular tissues. "Conversely, the deletion of Interferon regulatory factor 5 (IRF-5) coding genes provoked a reduction in IFNα and autoantibodies production, with an important improvement in kidney inflammation and damage." (PMID 36555640, 2022). "IRF5 is also activated downstream of Toll-like receptor (TLR) signaling in response to microbial components in the gut, thereby enhancing innate immune responses and contributing to chronic inflammation in UC." (PMID 41007813, 2025).
kidney disease (4 papers, 2014 to 2024). "An epigenome-wide association study for eGFR and ACR showed that DNA methylation at IRF5 was associated with kidney disease and a Mendelian randomization indicated a causal effect on eGFR." (PMID 37978231, 2023). "To assess whether the deletion of 1 allele of IRF5 in B cells might impact renal disease, we measured glomerular inflammation and injury as well as interstitial disease in kidneys from 4- to 5-month-old IRF5F/+ and IRF5ΔB mice." (PMID 34197340, 2021). "In this population-based cohort, that was mainly healthy at baseline, IRF5 genetic variation was associated with eGFR and ACR at baseline, and with the incidence of renal disease assessed by three different criteria." (PMID 37978231, 2023). "Approximately half the IRF5+/+ MRL/lpr mice had developed severe renal disease by the end-point of the study at 16 weeks of age as evidenced by the presence of glomerular crescents or necrosis." (PMID 25076492, 2014). "However, approximately half the IRF5+/+ MRL/lpr mice had less severe renal disease with serum BUN levels either normal or modestly elevated." (PMID 25076492, 2014). "IRF5−/− MRL/lpr mice had smaller spleens and lymph nodes, reduced titers of anti-nuclear and anti-dsDNA autoantibodies, lower levels of the complement-fixing IgG isotypes IgG2a, IgG2b and IgG3, less severe kidney disease and greatly improved survival." (PMID 25076492, 2014).
-immune diseases (3 papers, 2015 to 2025). "Genetic polymorphisms in IRF5 have been associated with multiple auto-immune diseases, including SSc47." (PMID 30872777, 2019). "Specifically, eight genes (IRF5, UBA7, TMTC1, GSTM3, FBN2, OAS1, PODXL, ITGA2) were previously associated with immune system diseases in at least one study." (PMID 25874939, 2015).
cardiovascular disease (3 papers, 2014 to 2020). "We further demonstrate that RIH or glucose fluctuations in vitro upregulate the expression of IRF5 together with markers of inflammation and the cardiovascular disease marker MMP-9." (PMID 32806763, 2020).
hematologic disorder (3 papers, 2012 to 2018). A disease involving the hematopoietic system. "A final example of IRF5 dysregulation in disease comes from the field of hematologic malignancies." (PMID 30515152, 2018).
neurological disease (3 papers, 2012 to 2018). "We evaluated in sera and CSF of patients with MS and with other neurological diseases (OND) the humoral response against EBV/MAP peptides and the IRF5/MBP." (PMID 26956729, 2016).
infectious disease (1 paper, 2016). A disorder directly resulting from the presence and activity of a microbial, viral, or parasitic agent in humans. "Additionally, the disease/function networks that associated with AGE downregulated Casp1, Tlr3, Serp1, Irf1, Irf5, and Irf7 genes were involved in the antimicrobial response, inflammatory response, and infectious diseases." (PMID 27734935, 2016).
IRF5 also shares sentences with these, for which no sentence is quoted: diabetes (9 papers); colon cancer (4); scleroderma (4); metabolic syndrome (3); metastatic melanoma (3); neurodegenerative disease (3); osteosarcoma (3); type-2 diabetes (3); abdominal aortic aneurysm (2); Behcet disease (2); breast tumor (2); Crohn disease (2); Glucose intolerance (2); invasive ductal carcinoma (2); low grade glioma (2); necrotizing enterocolitis (2); non-small cell lung carcinoma (2); Oral ulcer (2); Thrombocytopenia (2); thrombosis (2); acute monocyte leukemia (1); age (1); AIDS (1); alcoholic fatty liver disease (1); ankylosing spondylitis (1); aortic atherosclerosis (1); Atherosclerotic lesion (1); autoimmune hepatitis (1); brain injury (1); Burkitt lymphoma (1).
A further 44 diseases each share a sentence with IRF5 in 1 paper.